TIPE2 (TNF alpha induced protein 8 like 2)
Diseases named in the same sentence as TIPE2 in open-access papers (continued):
Sharing a sentence is not in itself a finding about the gene and the disease.
abortion (1 paper, 2017). the ending of pregnancy by removing a fetus or embryo before it can survive outside the uterus. "By statistical analysis, we found that TIPE2 positive staining was significantly lower in decidual tissues of missed abortion patients than that in healthy control (p < 0.01)." (PMID 28851386, 2017). "In the present study, we firstly collected the decidual and chorionic tissues of missed abortion patients and healthy controls, and detected the expression of TIPE2 mRNA and protein in these tissues." (PMID 28851386, 2017). "The expression of TIPE2 mRNA and protein in decidua and chorion from 36 missed abortion patients and 36 healthy controls was detected using quantitative real-time PCR, western blot and immunohistochemistry." (PMID 28851386, 2017). "To investigate the expression status of TIPE2 proteins, we detected the protein levels of TIPE2 using western blot analysis in the decidua and chorion of missed abortion patients and healthy controls." (PMID 28851386, 2017). "To further investigate the expression sites and protein levels of TIPE2 in maternal-fetal interface, we measured the expression of TIPE2 in the decidual and chorionic tissues of missed abortion patients and healthy controls by IHC." (PMID 28851386, 2017). "In the present study, we detected the expression status of TIPE2 in decidua and chorion of missed abortion patients and healthy controls at both mRNA and protein level by quantitative real-time PCR, western blot and immunohistochemistry." (PMID 28851386, 2017). "Quantitative real-time PCR analysis was performed to detect the TIPE2 mRNA expression in the decidua and chorion of missed abortion patients and healthy controls." (PMID 28851386, 2017). "The statistic results confirmed that TIPE2 protein was only reduced in the decidual tissues of missed abortion patients compared with healthy controls." (PMID 28851386, 2017). "The results revealed that the expression of TIPE2 protein in decidual tissues was significantly lower in missed abortion patients than that in healthy controls (P < 0.01)." (PMID 28851386, 2017). "To further determine the expression sites and levels of TIPE2 proteins, we detected the TIPE2 proteins in the decidua and chorion of missed abortion patients and healthy controls by IHC." (PMID 28851386, 2017). "Our data indicate TIPE2 could play important roles in maintaining the maternal-fetal tolerance and decreased TIPE2 expression in the decidua may be related to the development of missed abortion." (PMID 28851386, 2017).
adenomyosis (1 paper, 2022). The growth of endometrial tissue inside the muscular wall of the uterine corpus. "In addition, studies have shown that TIPE2 expression is down-regulated in adenomyosis, suggesting that TIPE2 plays an important role in inhibiting the migration and invasion of endometrial cells." (PMID 35388275, 2022).
adenosquamous carcinoma (1 paper, 2019). A carcinoma composed of malignant glandular cells and malignant squamous cells. "Further, TIPE2 displayed around 2-fold increase in its expression in adenosquamous cell carcinoma tissues, whereas it exerted around 3-fold increase in its expression in large cell carcinoma tissues compared to the normal human lung tissues." (PMID 31817720, 2019).
ankylosing spondylitis (1 paper, 2021). An autoimmune chronic inflammatory disorder characterized by inflammation in the vertebral joints of the spine and sacroiliac joints. "The significant increase in TIPE2 expression in patients with ankylosing spondylitis (AS) is accompanied by a negative correlation with the expression of inflammatory cytokines, which is also speculated to maintain immune homeostasis and inhibit a hyperinflammatory response." (PMID 33815396, 2021).
Ascites (1 paper, 2019). Accumulation of fluid in the peritoneal cavity (between the layers of the peritoneum that lines the abdomen). "Furthermore, there was a significant difference in TIPE2 mRNA between LC patients with ascites and without ascites." (PMID 31661000, 2019).
cardiac hypertrophy (1 paper, 2022). "In summary, TIPE2 protects against adverse cardiac hypertrophy by targeting TLR4 in the membrane of macrophages in the heart and subsequently attenuating prohypertrophic Akt signaling in cardiomyocytes." (PMID 35528518, 2022). "TIPE2 overexpression attenuated pressure overload-induced cardiac hypertrophy, fibrosis, and cardiac dysfunction." (PMID 35528518, 2022). "The present study elucidated for the first time that TIPE2 is downregulated in the progression of cardiac hypertrophy to heart failure and that TIPE2 overexpression inhibits pressure overload-induced cardiac hypertrophy, fibrosis, and dysfunction." (PMID 35528518, 2022). "Intercellular and perivascular fibrosis, which is another characteristic of cardiac hypertrophy, was also alleviated in the TIPE2-overexpressing group." (PMID 35528518, 2022). "In the present study, we used aortic banding (AB) to establish a cardiac hypertrophy model to elucidate the functional role of TIPE2 in chronic heart insult." (PMID 35528518, 2022). "TAK-242 relieved cardiac hypertrophy in the same manner as TIPE2 overexpression." (PMID 35528518, 2022). "Thus, the aim of the present study was to explore the role of TIPE2 in cardiac hypertrophy." (PMID 35528518, 2022). "The present study indicated that TIPE2 represses macrophage activation by targeting TLR4, subsequently inhibiting cardiac hypertrophy." (PMID 35528518, 2022). "Similar to the effect of TIPE2 overexpression, treatment with a TLR4 inhibitor mitigated the adverse cardiac hypertrophy." (PMID 35528518, 2022). "The role of TIPE2 in cardiovascular disease, especially cardiac hypertrophy, has not been elucidated." (PMID 35528518, 2022).
cervical adenocarcinoma (1 paper, 2019). An adenocarcinoma arising from the cervical epithelium. "So far only one previous paper reported that TIPE2 was down-regulated in cervical adenocarcinoma HeLa cells." (PMID 33817189, 2019).
cervical squamous cancer (1 paper, 2019). "Cervical squamous cancer cell lines, SiHa and C33A, were transfected with recombinant plasmid encoding TIPE2 and tested for cytologic characteristics." (PMID 33817189, 2019). "In conclusion, our study further showed that down-regulation of TIPE2 was associated with the development of cervical squamous cancer." (PMID 33817189, 2019). "TIPE2 is an inhibitory factor of proliferation and invasion of cervical squamous cancer cells, probably through inhibiting Erk signaling pathway." (PMID 33817189, 2019). "We found that TIPE2 inhibited growth, migration, and metastasis of cervical squamous cancer cells, SiHa and C33A, via suppressing phosphorylation of Erk1/2." (PMID 33817189, 2019). "This study further investigated the role of TIPE2 on proliferation and invasion of cervical squamous cancer cells." (PMID 33817189, 2019). "Expression of TIPE2 was compared in cervical squamous cancer tissues and adjacent normal tissues by Western blot and immunohistochemistry (IHC)." (PMID 33817189, 2019). "In our study, TIPE2 expression in cervical squamous cancer tissues was down-regulated compared with that in normal adjacent tissues, and was associated with lymphatic metastasis." (PMID 33817189, 2019). "TIPE2 is negatively related with development of cervical squamous cancer." (PMID 33817189, 2019). "Therefore, we investigated the role and possible molecular mechanism of TIPE2 on proliferation and invasion of cervical squamous cancer cells." (PMID 33817189, 2019).
chronic kidney disease (1 paper, 2025). Impairment of the renal function secondary to chronic kidney damage persisting for three or more months. "Inflammation is insufficiently balanced in chronic kidney disease, as the translational activity of the anti-inflammatory mediators IL-10 and TIPE2 are not different either between N and H or between HD and CO." (PMID 41009490, 2025).
cognitive decline (1 paper, 2023). "This study aimed to examine the role of TIPE2 in isoflurane-induced postoperative cognitive decline (POCD)." (PMID 37069964, 2023).
Cognitive impairment (1 paper, 2023). Abnormal cognition is characterized by deficits in thinking, reasoning, or remembering. "Our study demonstrated that TIPE2 deficiency caused further aggravation of cognitive impairment in mice compared to control mice." (PMID 37069964, 2023). "TIPE2 deficiency aggravated cognitive impairment in mice and further caused apoptosis and oxidative stress in hippocampal neurons." (PMID 37069964, 2023). "TIPE2 inhibits the activation of microglia by regulating the STAT3 and NF-κB pathways, improves the antioxidative and anti-inflammatory ability of hippocampal neurons, and inhibits apoptosis, thereby alleviating cognitive impairment." (PMID 37069964, 2023).
diffuse large B-cell lymphoma (1 paper, 2019). "A similar observation was reported by Hao and colleagues, where enhanced expression of TIPE2 was found in both diffuse large B-cell lymphoma and peripheral T-cell lymphoma." (PMID 31817720, 2019).
encephalomyelitis (1 paper, 2021). Inflammation of the brain and the spinal cord. "Tumor necrosis factor-a-induced protein 8-like 2 (TNFAIP8L2, TIPE2) was identified for the first time in experimental organ encephalomyelitis (EAE) mice." (PMID 33850476, 2021).
Erythema (1 paper, 2019). Redness of the skin, caused by hyperemia of the capillaries in the lower layers of the skin. "IMQ-induced skin inflammation in TIPE2-deficient mice resulted in lower scores for erythema and scaling at the peak-stage of the disease." (PMID 31616442, 2019).
ischemia (1 paper, 2020). A hypoperfusion of the BLOOD through an organ or tissue caused by a PATHOLOGIC CONSTRICTION or obstruction of its BLOOD VESSELS, or an absence of BLOOD CIRCULATION. "To determine if TIPE0 modulated intestinal injury in an acute injury model without a regenerative component, we subjected both Tipe0−/− and Tipe2−/− mice to 60 min of distal ileal ischemia followed by 90 min of reperfusion (I/R90′)." (PMID 32444641, 2020).
lentivirus infection (1 paper, 2016). Virus diseases caused by the Lentivirus genus. "To determine whether TIPE2 is involved in tumor’s DNA damage/repair, we generated Huh7-TIPE2-overexpressing stable cell line and Changliver-TIPE2 knockdown stable cell line by using lentivirus infection." (PMID 27696294, 2016).
liver cirrhosis (1 paper, 2019). "This is the first report to investigate the expression of TIPE2 in HBV-associated liver cirrhosis." (PMID 31661000, 2019). "TIPE2 mRNA was associated with various stages of chronic HBV infection, ranging from CHB to liver cirrhosis and HCC." (PMID 31661000, 2019). "In liver cirrhosis, the TIPE2 mRNA level in the decompensated state was significantly higher than that in the compensated state (P < 0.05)." (PMID 31661000, 2019). "We demonstrated that the relative level of TIPE2 mRNA in liver cirrhosis was similar to that in CHB patients, whereas the TIPE2 mRNA level in decompensated LC patients was higher than that in compensated LC patients." (PMID 31661000, 2019). "However, the exact mechanism of TIPE2 in liver cirrhosis should be well investigated in future studies." (PMID 31661000, 2019). "We reported that TIPE2 mRNA is positively correlated with the MELD score in liver cirrhosis." (PMID 31661000, 2019). "Furthermore, the optimal cutoff of 0.78 for the level of TIPE2 mRNA has a sensitivity of 97.56% and a specificity of 88.16% for discriminating HCC from patients with CHB and liver cirrhosis." (PMID 31661000, 2019). "However, TIPE2 mRNA was not significantly related to age, sex, HBeAg, liver cirrhosis, multiple primary tumor number and serum AFP level." (PMID 31661000, 2019). "In other nonviral liver cirrhosis, TIPE2 might also exert its unique role." (PMID 31661000, 2019).
liver failure (1 paper, 2017). A liver disease characterized by the liver losing or has lost all of its function. "Currently, we have previously revealed that TIPE2 contributed to the occurrence of liver failure and peripheral TIPE2 mRNA level might be a biomarker for predicting the 3-month mortality of liver failure." (PMID 28390195, 2017).
Lymphatic Metastasis (1 paper, 2019). Transfer of a neoplasm from its primary site to lymph nodes or to distant parts of the body by way of the lymphatic system. "However, the TIPE2 score was associated with lymphatic metastasis (P=0.014)." (PMID 33817189, 2019).
muscular dystrophy (1 paper, 2023). Muscular dystrophy (MD) refers to a group of more than 30 genetic diseases characterized by progressive weakness and degeneration of the skeletal muscles that control movement. "The over-expression of TIPE2 significantly lowered the proliferation of macrophages and inhibited the secretion of pro-inflammatory factors, becoming a new anti-inflammatory therapy to alleviate muscle weakness in patients with muscular dystrophy." (PMID 36983674, 2023).
ovarian carcinoma (1 paper, 2023). A malignant neoplasm originating from the surface ovarian epithelium. "TIPE2 was shown to be associated with tumor-infiltrating immune cells in the TME of ovarian cancer." (PMID 36801818, 2023). "Furthermore, TIPE2 was closely associated with the infiltration of TILs in ovarian cancer, lending credence to TIPE2’s putative immunological role in ovarian cancer." (PMID 36801818, 2023). "Finally, TIPE2 expression was positively associated with various immune cells and possibly involved in the regulation of macrophage polarization in ovarian cancer." (PMID 36801818, 2023). "With the help of the online database, we further explore the link between TIPE2 and immune infiltration in ovarian cancer." (PMID 36801818, 2023). "The CIBERSORT was then utilized to further quantify the proportion of immune cells in ovarian cancer with low and high TIPE2 expression." (PMID 36801818, 2023). "It urges us to explore the molecular foundations of TIPE2 as well as tumor-immune interactions in ovarian cancer in the future." (PMID 36801818, 2023). "Taken together, our findings suggest that TIPE2 may play a role in ovarian cancer immunology and that TIPE2 might be exploited as a novel immunotherapy target for ovarian cancer." (PMID 36801818, 2023). "TIPE2 has the potential to be employed as a therapeutic target and checkpoint in ovarian cancer." (PMID 36801818, 2023). "TIPE2 is a crucial regulator of immunological homeostasis, thus TISIDB and TIMER platforms were utilized to further explore the relationship between TIPE2 and TME in ovarian cancer." (PMID 36801818, 2023). "Significant correlations were observed between TIPE2 expression and CD8+ T cells, T cell exhaustion (immune checkpoint genes), general T cells, Th1, Th2, Tfh, Treg, B cells, monocyte, M1 macrophages, M2 macrophages, neutrophils, NK cells in ovarian cancer." (PMID 36801818, 2023). "TIPE2 may participate in TAM polarization towards an M1 phenotype and play anti-tumoral functions in the TME of ovarian cancer, which must be explored further." (PMID 36801818, 2023). "The results showed that TIPE2 expression correlated positively with the tumor-infiltrating immune cells in ovarian cancer, including CD8+ T cells, CD4+ T cells, Treg cells, activated DCs, NK cells, macrophages, mast cells, and Tfh, suggesting that TIPE2 may impair the TME of ovarian cancer." (PMID 36801818, 2023). "Therefore, a TIPE2-stimulated co-culture system of ovarian cancer cells and macrophages may be conducted to further investigate whether TIPE2 can drive macrophage polarization in the TME of ovarian cancer." (PMID 36801818, 2023).
pancreatic ductal adenocarcinoma (1 paper, 2021). An infiltrating adenocarcinoma that arises from the epithelial cells of the pancreas. "However, the expression and roles of TIPE2 in pancreatic ductal adenocarcinoma (PDAC) are largely unknown." (PMID 33850476, 2021).
Parkinson disease (1 paper, 2018). A progressive degenerative disorder of the central nervous system characterized by loss of dopamine producing neurons in the substantia nigra and the presence of Lewy bodies in the substantia nigra and locus coeruleus. "Another study conducted by Kouchaki and group attempted to evaluate the association between the serum levels and circulatory gene expression of TIPE2 with severity of Parkinson’s disease by enrolling a total of 43 patients." (PMID 30274259, 2018). "They further showed that enhanced serum levels of TIPE2 possess a direct correlation with age and severity of patients with Parkinson’s diseases." (PMID 30274259, 2018).
periodontitis (1 paper, 2023). An acute or chronic inflammatory process that affects the tissues that surround and support the teeth. "Interventions aimed at increasing TIPE2 may help in the therapeutic applications for periodontitis." (PMID 37493703, 2023).
primary biliary cirrhosis (1 paper, 2019). "For example, decreased expression of TIPE2 has been reported to be associated with the hyperreactivity of monocytes to toll-like receptor ligands in primary biliary cirrhosis." (PMID 31661000, 2019).
skin inflammation (1 paper, 2019). "This theory may also explain why the IMQ-induced skin inflammation of TIPE2-deficient mice is only marginally reduced compared with that of WT mice." (PMID 31616442, 2019).
Streptococcus pneumoniae infection (1 paper, 2021). "We report here that TIPE proteins (TNFAIP8 and TIPE2) protect mice at mucosal sites from local Streptococcus pneumoniae infection by regulating lymphocyte homing, as directed by CCR9." (PMID 34939151, 2021).
ulcerative colitis (1 paper, 2017). An inflammatory bowel disease involving the mucosal surface of the large intestine and rectum. "On the other hand, TIPE2 mRNA expression was increased in patients with acute chronic hepatitis B liver failure or ulcerative colitis." (PMID 29152095, 2017).
urothelial carcinoma (1 paper, 2025). A malignant neoplasm derived from the transitional epithelium of the urinary tract (urinary bladder, ureter, urethra, or renal pelvis). "Therefore, focus of the present research was to explore the relationship between immunohistochemical expression of TIPE2 and CD36 in urothelial carcinoma and clinicopathological findings and prognosis." (PMID 40060230, 2025).